MMP2 (matrix metallopeptidase 2)
Diseases named in the same sentence as MMP2 in open-access papers (continued):
Sharing a sentence is not in itself a finding about the gene and the disease.
melanoma (512 papers, 1999 to 2026). A malignant, usually aggressive tumor composed of atypical, neoplastic melanocytes. "Another study investigated NCTD’s impact on melanoma, finding that it suppresses tumor growth and inhibits metastasis by downregulating MMP-2 expression, a protein linked to cancer cell invasion." (PMID 39940982, 2025). "Conversely, reduced MMP-2 expression in melanoma cells has been linked to the inhibition of IL-23-induced invasiveness." (PMID 39780275, 2025). "In canine malignant melanoma, increased MMP-2 and MMP-9 expression has similarly been associated with enhanced invasiveness, suggesting conserved mechanisms between species." (PMID 41394861, 2025). "High B7-H3 expression has been linked to enhanced migration and invasion capabilities of melanoma cells through the upregulation of MMP2 and modulation of the STAT3 pathway." (PMID 40801642, 2025). "High levels of MMP-2 were associated with poor prognosis in melanoma patients, as well as in BLM xenografts with a significant correlation with the increased malignancy." (PMID 38247872, 2024). "The downregulation of mmp2 and rpsa, markers associated with melanoma invasion, further substantiates the role of these alkaloids in inhibiting melanoma progression." (PMID 39598801, 2024). "Specifically, the expression level of MMP-2 has been shown to be associated with poor prognosis in patients carrying BRAF-mutated melanoma." (PMID 37507910, 2023). "Other commonly evaluated markers were some of those that have previously been reported as VM-associated in melanoma, including MMP-2, MMP-9, and EphA2." (PMID 36823554, 2023). "In this study, we evaluated the association between MMPs and melanoma prognosis using TCGA database, and found that MMP2 low expression benefited patients the most." (PMID 36788565, 2023). "A major cancer related MMP is the gelatinase MMP-2, which is often upregulated in melanoma and is closely associated with invasion and metastasis." (PMID 36005056, 2022). "Dendritic cells (DCs) with MMP-2 initiates TH2 responses against several melanoma-associated antigens." (PMID 36776395, 2022). "Elevated expression of some MMPs (such as MMP2, MMP1, and MMP13) has been directly correlated with poorer prognosis, and MMP2 — in particular — has been associated with melanoma progression." (PMID 34032639, 2021). "Among these, MMP2 is overexpressed (OE) in many tumors, including melanoma, and high MMP2 levels in tumor or stromal cells are associated with increased tumor invasion and cancer progression, with patients often having poorer survival/prognosis." (PMID 34032639, 2021). "First, MMP2 is a bona fide melanoma-associated self-antigen that is recognized by both CD4+ and CD8+ T cells present in patient TILs." (PMID 34032639, 2021). "Hypoxia-induced secretion of MMP2 (matrix metalloproteinase 2) by senescent cells was also implicated in facilitating the invasion of melanoma cells." (PMID 33918883, 2021). "The αvβ3 integrin overexpression in melanoma cells is associated with induction of bcl2 to prevent apoptosis, and matrix metalloproteinase (MMP)-2 to break down the collagen of the basement membrane." (PMID 34067929, 2021). "Increased MMP-2 activity is associated with poor prognosis in such types of cancer as colon, breast, melanoma, ovary, prostate and lung cancers." (PMID 33198257, 2020). "The deregulated expression of MMP2 is thought to be involved in multiple pathways disorders causing cancers such as GC cancer, colorectal cancer, melanoma, and prostate cancer." (PMID 30568862, 2018). "Melanoma-CM also influenced the expression of matrix genes as well as genes encoding proteins that impact on matrix remodelling, such as MMP2 and TIMP1." (PMID 29545604, 2018). "Overall, these results further indicate that LKB1 low levels are negatively linked to MMP-2 high levels in BRAF V600E human melanoma tissues." (PMID 29371951, 2017).
melanoma (continued). "Strong MMP-2 expression is prevalent in primary and metastatic melanomas as compared to normal and dysplastic nevi, and is associated with worse survival of melanoma patients." (PMID 26911838, 2016). "It is reported that MMP2 was frequently associated with malignant progression and poor prognosis in melanoma." (PMID 25671570, 2015). "Having previously found six independent prognostic biomarkers in melanoma, including BRAF, MMP2, p27, Dicer, Fbw7 and Tip60, our group has gone on to investigate if these markers are useful in risk stratification of melanoma patients in individual AJCC stages." (PMID 25784655, 2015). "The melanoma lines showed highly different invasion patterns, and differences in invasiveness was associated with differences in expression of MMP-2 and MMP-9." (PMID 26667022, 2015). "Strong MMP2 expression is associated with worse melanoma patient survival and is an independent prognostic factor for primary melanoma." (PMID 26329521, 2015). "The PI-3 kinase network mediated by MMP-2 upregulation has previously been implicated in melanoma VM, consistent with our observation that MMP-2 was one of the most downregulated genes in response to FGFR or VEGF inhibition." (PMID 26203665, 2015). "In a complementary study, MMP-2 wild-type B16-BL6 melanoma cells implanted into MMP-2 deficient host mice also exhibited slightly decreased tumor growth and a significant delay in lung colonization after intravenous injection." (PMID 24978435, 2014). "In melanoma, increased expression of MMP-2 is associated with high invasiveness and melanoma progression, while expression of MMP-9 was associated with metastasis." (PMID 25491880, 2014). "For example, in melanoma, elevated MMP-2 expression has been associated with increased levels of MCAM and NCAM." (PMID 22272201, 2012). "The more aggressive behaviour of different Bcl-2 overexpressing melanomas was associated to an increase in several metalloproteases (e.g. MMP-2, MMP-7, and MT1-MMP) expression, and to an elevated microvessel density as compared to parental cells." (PMID 22233801, 2012). "αvβ3 Integrin expression in human melanomas promotes invasion through physical interaction with MMP-2, and inducing transendothelial migration by association with the human neural cell adhesion molecule L1 expressed on endothelium." (PMID 20860798, 2010). "On the other hand, the controversial and dual role of MMP2 emerges from its association with improved overall survival rates in melanoma patients with a higher mutation burden due to its activity of freeing extracellular matrix (ECM) structural protein mutants adjacent to MMP2‐sensitive sites." (PMID 38775220, 2024). "Similarly, baicalein significantly inhibited migration and invasion of melanoma cells by suppressing MMP-2 and -9 expression and activity associated with the suppression of the phosphoinositide 3-kinase/AKT signaling pathway." (PMID 36829966, 2023). "Furthermore, wogonin causes suppression of melanoma cell B16-F10 migration, adhesion, invasion and actin remodeling by inhibiting MMP-2." (PMID 37560476, 2023). "Moreover, MMP2 is uniformly elevated across melanoma cell lines and has also been associated with more invasive cancers and poorer prognoses." (PMID 35316219, 2022). "Moreover, MMP2 has also been identified as a melanoma-associated antigen that is recognized by tumor-infiltrating lymphocytes (TILs), suggesting a dual role in promoting tumor growth as well as in engaging antitumor immunity." (PMID 34032639, 2021). "The breakdown of the ECM, primarily by MMP-2 in melanoma causes the exposure of integrin-ECM binding sites in the ECM that can increase migration, but also the cleavage of other cell surface proteins (e.g., cadherins) that can increase the cellular signal to metastasise." (PMID 34439879, 2021).
melanoma (continued). "MMP-2 and -9 are secreted MMPs in the group of collagenases, also known as collagenases A and B, respectively, and appears to be associated with radial and vertical growth and with metastasis in melanoma." (PMID 30891426, 2019). "Both CSPG4 and MMP2 have previously been implicated in melanoma progression." (PMID 27926479, 2017). "In addition, LKB1 expression in human melanoma tissues was negatively associated with MMP-2 expression in the presence of BRAF V600E." (PMID 29371951, 2017). "In addition to the impact of CSPG4 on aggressiveness of melanoma, matrix metalloproteinase (MMP)-2, or gelatinase A, has also been associated with increased invasiveness of malignant melanoma, due to effects on the degradation of the extracellular matrix." (PMID 27926479, 2017). "In melanoma, MMP-2 and MMP-9 overexpression has been associated with EMT, invasion, and metastasis." (PMID 26517521, 2016). "Over-expression of MMP2 or MMP9 is often associated with melanoma metastasis and lesions." (PMID 26769849, 2016). "Overexpression of MMP-2 has been implicated in melanoma progression and survival." (PMID 26517521, 2016). "Recent studies have also shown that MMP2 is associated with the survival of patients with melanoma." (PMID 25954957, 2015). "MMP2 has been shown to be associated with melanoma progression." (PMID 26293674, 2015). "Our data suggest that MMP-2 may be associated with bone invasion also in melanoma, and this warrants further investigations." (PMID 26667022, 2015). "MCAM, MMP-2, and Gal-3 expression in primary melanoma have been linked to poorer overall survival and could be used in combination with current prognostic indicators to identify patients at high-risk of recurrence." (PMID 24069584, 2013). "In melanoma, MMP-2 has frequently been associated with malignant progression and poor prognosis." (PMID 24069584, 2013). "The association of these membrane glycoproteins with MMP-2 activation is of particular interest because αvβ3 integrin is often highly expressed on melanoma, claudin-1 expression levels increase with increasing thickness of the primary lesion and CSPG4 is potentially a useful biomarker for melanoma." (PMID 24069584, 2013). "Thus, MMP-2 is very strongly associated with invading vertical growth melanomas." (PMID 24069584, 2013). "MMP‐14 is particularly relevant in melanoma progression as it activates other MMPs, such as MMP‐2 and promotes tumour cell migration by cleaving ECM components." (PMID 41546170, 2026). "It modulated melanoma cell metastasis by reducing MMP‐2 and MMP‐9 expression through the inhibition of the FAK/PI3K/Akt/mTOR, MAPK and GRB2 signalling pathways." (PMID 41546170, 2026). "The inhibition of the MMP‐2 level by siRNA resulted in a significant reduction in A375 and A375mA2 cell migration and invasion, indicating the direct involvement of MMP‐2 in melanoma invasion and/or migration." (PMID 41546170, 2026). "Extensive research has been concentrated on identifying and developing MMP inhibitors for cancer treatment, including melanoma, with particular focus on MMP‐2, MMP‐9 and MMP‐14." (PMID 41546170, 2026). "The efficacy of this cyclic peptide in modulating cellular MMP‐2 activities and inhibiting cell migration has been confirmed in a human melanoma cell line." (PMID 41546170, 2026). "MMP-9 serves as an established marker of melanoma invasiveness, and MMP-2 functions as a pro-metastatic factor during melanoma progression." (PMID 40872552, 2025). "MMP-14, in particular, is known to activate MMP-2, enhancing the invasive potential of melanoma cells." (PMID 40604111, 2025). "This interaction is reciprocal: metastatic melanoma cells induce the production, by astrocytes, of pro-inflammatory factors such as IL-23, and on the other hand, factors such as MMP2 are produced." (PMID 40507830, 2025).
melanoma (continued). "It exhibits strong inhibitory activity against MMP-2, and its overexpression has been shown to suppress melanoma cell proliferation, partly through modulation of the Wnt/β-catenin signalling pathway." (PMID 40869222, 2025). "IL-8 enhances the activity of MMP-2 secreted by melanoma cells, which in turn promote melanoma invasion." (PMID 39866233, 2025). "Matrix metalloproteinase 2 (MMP2) and interleukin-8 (IL-8) are secreted by melanoma in acidic environments, and they can accelerate the degradation of the extracellular matrix and enhance the invasion and metastasis of tumor cells." (PMID 40539068, 2025). "In melanoma (B16-F10 and A375) cells, emodin decreases MMP-2 and MMP-9 protein expression, suppressing migration and invasion." (PMID 40490812, 2025). "Study shows that upregulation of MMP-2 in the tumor microenvironment can lead to vemurafenib resistance in melanoma." (PMID 40703348, 2025). "In melanoma (B16-F10 and A375) cells, its ability to decrease MMP-2 and MMP-9 protein expression and suppress the Wnt/β-catenin pathway suggesting a therapeutic strategy for highly metastatic tumors." (PMID 40490812, 2025). "Our findings demonstrate that mTOR kinase inhibitors from three successive generations, particularly when used in combination with MEK1/2 inhibition, significantly reduce melanoma cell invasiveness and downregulate metalloproteinases MMP-2 and MMP-9." (PMID 40869090, 2025). "For instance, E-cadherin loss stabilizes c-JUN protein and upregulates target genes, such as MMP-9, MMP-14 and MMP-2, key factors in driving melanoma metastasis." (PMID 40399946, 2025). "Melanoma cell adhesion is enhanced by the coupling of αvβ3 integrin with the α3(IV) chain, which simultaneously reduces cancer spread by suppressing MMP-2 expression." (PMID 40399946, 2025). "Inhibiting TGF-β1-induced MMP-2 expression and cell migration has been shown to effectively decrease invasion and metastasis in lung carcinoma and melanoma." (PMID 40806251, 2025). "Their study also confirmed that IL-8 inhibition significantly reduces the expression of extracellular matrix metalloproteinase 2 (MMP-2), thereby reducing the angiogenic potential of melanoma cells and providing lung metastasis." (PMID 38656555, 2024). "The invasive potential of melanoma cells was assessed by analyzing MMP-2 and -9 activity in cell culture supernatants using SDS-zymography." (PMID 38247872, 2024). "The action of GH, particularly in the presence of doxorubicin, in promoting exosomal N-cadherin and MMP2, along with accelerated cell migration, indicates a potential role of GH in disseminating these proteins to treatment-naïve melanoma cells via exosomes." (PMID 39123364, 2024). "Invasion and metastatic potential of melanoma cells is driven, i.e., by MMP-2 on hypoxia-dependent pattern." (PMID 39769454, 2024). "Elevated levels of MMPs, such as MMP-2 and MMP-9, are commonly observed in melanoma and are associated with aggressive tumor behavior." (PMID 39200315, 2024). "Effective inhibition of MT1-MMP and MMP2 activity resulting in reduction in melanoma cells growth, migration and invasion in vitro." (PMID 39594665, 2024). "More and more emerging evidence proves the pro‐oncogenic, and specifically immunosuppressive role, of MMP2 in melanoma, since its overexpression is closely related to the increased infiltration of CAFs." (PMID 38775220, 2024). "Microarray gene microarray analyses have shown a significant increase in MMP2 expression in aggressive melanoma cells compared to poorly invasive melanoma cells, which are required for increased MMP2 expression for VM." (PMID 38664375, 2024). "Melanoma cells remodel microglia and upregulate matrix metalloproteinase-2 (MMP2) secretion to enhance cell proliferation and migration." (PMID 37307835, 2024).
melanoma (continued). "MMP-2 directly modulates melanoma cell adhesion, ECM spreading, and invasion, while its inhibitors inhibit growth and tumor neovascularization by preventing MMP-2 binding to αvβ3 and blocking cell surface collagenolytic activity." (PMID 38672182, 2024). "In human melanoma, MMP2 appears dramatically overexpressed in metastatic melanoma cells compared to primary tumor cells." (PMID 38775220, 2024). "Baicalein also suppressed melanoma cell migration and invasion by inhibiting MMP-2 and -9 expression and activity and the phosphoinositide 3-kinase/AKT signaling pathway." (PMID 38398617, 2024). "Melanoma A-2058 is characterized by elevated secretion of both MMP-2 and -9 in comparison to normal cells." (PMID 39335164, 2024). "The shift from primary to metastatic melanoma has been linked to overexpression of integrins αvβ3, αvβ5, α2β1, and α5β1 and, consequently, overexpression of integrins increases the propensity of melanoma cells to invade by stimulating MMP-2 and MMP-7." (PMID 38791873, 2024). "Matrix metalloproteinase 2 (MMP2) has been identified as a biomarker associated with BRAF mutations and is negatively correlated with survival in patients with BRAF-mutant melanoma, yet its application in clinical practice is limited." (PMID 39336897, 2024). "The inhibition of mmp2 and rpsa not only suggests a mechanism through which the compounds prevent the spread of melanoma cells but also aligns with the broader need for therapies that target the invasive nature of this cancer." (PMID 39598801, 2024). "For instance, IL-23 supports melanoma brain metastases’s progression and invasion, with melanoma brain metastatic cells upregulating MMP2-mediated IL-23 expression in astrocytes." (PMID 38231464, 2024). "We observed a reduction in migration and invasion of both melanoma cell lines associated with reduced activity of MMP-9 and MMP-2 when treatment with GlaB and C22 was performed." (PMID 38399442, 2024). "Melanoma-derived MMP-2 regulates VEGF expression by activating integrin αVβ5 through an autocrine mechanism." (PMID 39769318, 2024). "Other markers noted in studies that identified VM-capable glioblastoma cells were expression of VE-cadherin, MMP-2, MMP-9, and EphA2, all of which have previously been associated with VM in melanoma." (PMID 36823554, 2023). "On the other hand, melanoma cells cross-present secreted MMP2 to human leukocyte antigen A*0201-restricted T cells in an αvβ3-dependent manner." (PMID 36788565, 2023). "It has been found that MMP-2 and -9 are expressed in human melanoma and that MMP-2 is associated with melanoma progression." (PMID 37894438, 2023). "MMP2 inhibitor works synergistically with PD-1 antibody and induces tumor regression in a mouse melanoma model, which is dependent on decreased CAFs infiltration." (PMID 36788565, 2023). "Among all the synthesized inhibitors that were tested against melanoma and PT-67 fibroblast cell lines, compounds 19 and 20 showed the best inhibition of MMP-2, with a concentration of 20 and 10 μM, respectively." (PMID 37513440, 2023). "For example, MMP2, produced by melanoma cells after exposure to astrocyte-secreted IL-23, has been shown to promote diapedesis of human melanoma cells in a human BBB model." (PMID 37894438, 2023). "For example, in melanoma cells, upstream matrix metallopeptidase 2 (MMP2)/RAC1 signalling is increased, which results in negatively regulating the tumor suppressor function of SPRY4." (PMID 36384366, 2023). "It reduces the migratory ability of melanoma cells through the regulation of E‐cadherin/vimentin and MMP‐2/MMP‐9 expression." (PMID 37038620, 2023). "According to a mouse melanoma model, we found that MMP2 inhibitor synergistically with PD-1 antibody induces tumor regression, which dependent on decreased CAFs infiltration." (PMID 36788565, 2023).